TGFB1 (transforming growth factor beta 1)
Diseases named in the same sentence as TGFB1 in open-access papers (continued):
Sharing a sentence is not in itself a finding about the gene and the disease.
glioma (continued). "TGFB1, VEGFA, ARG1, and IL10 are secreted immunosuppressive factors in glioma, while CD70 is a glioma cell-surface immunosuppressive factor." (PMID 37891828, 2023). "While the glioma–GAM signaling axis is complex, transforming growth factor-beta 1 (TGFβ1) has been identified as a key signaling molecule mediating tumor invasion, migration, and immunosuppression in GBM." (PMID 37368789, 2023). "We found that TPM4 is related to the molecular targets of glioma, such as CD160, IDO1, IL10, KDR, PVRL2, and TGFB1." (PMID 36639743, 2023). "In the next part of the study, changes in the expression levels of TGFβ1, TGFβ2, TGFβ3, and ACTB were evaluated in gliomas with different degrees of malignancy." (PMID 35454784, 2022). "A recent comparative RNA-seq analysis identified that many genes are commonly upregulated in both gliomas (eg., IDH wild-type) and BrMs, including the angiogenic factor VEGFA, growth factors PDGFA, TGFB1, SPP1, and the protease inhibitor TIMP-116." (PMID 36216799, 2022). "Our in vitro glioma IHC analysis also confirmed the riskscore positively correlated with IBA1, TMEM119, CD68, CSF1R, and TGFB1 protein expression." (PMID 35985661, 2022). "TGFB1, VEGFA, ARG1, FGL2 and IL10 are secreted immunosuppressive factors in glioma, while CD95L and CD70 are glioma cell‐surface immunosuppressive factors." (PMID 33611848, 2021). "Despite the documented roles of TGFB1, SPARC and LAMA4 in GBM progression and invasion, only the SPARC protein was identified in the two clinical glioma EV preparations profiled here." (PMID 27770278, 2017). "β-catenin is an important glioma promoter, while recent studies have discovered that SND1 promotes oncogenesis and progression through increasing TGFβ1 pathway activity." (PMID 28160566, 2017). "Further, many of the inhibited upstream regulators identified have strong pro-tumor activities (e.g., TGFB1, which increases glioma malignancy), consistent with the overall strong anti-tumor responses that we have seen in the metronomic CPA-treated gliomas." (PMID 25952672, 2015). "TGFβ1 increased glioma-initiating cells (GICs) self-renewal through the induction of LIF and the JAK-STAT pathway, and TGFβ inhibitors were emerging as compounds targeting GICs." (PMID 25978454, 2015). "For example, transforming growth factor-beta 1 (TGF-β1), an immunosuppressive cytokine that is expressed by glioma cells, is also produced by GAMs." (PMID 23864876, 2013). "Finally, miR-133b-3p, which possibly targets TGFB1 transcripts, bound directly to the Lnc HOXA transcript antisense RNA, myeloid-specific 1 (HOTAIRM1) in high-grade gliomas and in malignant transformed fibroblasts." (PMID 38571882, 2024). "Furthermore, another study reported that sex-determining region Y-box 4/2 (SOX4/2), including SOX2 and SOX4, induced by the SMAD2/3 pathway, which is activated by TGFβ1 (mainly from M2 TAM), promotes the stemness and migration abilities of glioma cells." (PMID 37759870, 2023). "In glioma, POSTN may regulate resistance to anti-VEGF-A therapy by upregulating the expression of TGFβ1 and HIF1α." (PMID 37180146, 2023). "Importantly, the Siglec-15 expression level was positively correlated with macrophage infiltration in glioma and phenotypic markers of M2-like macrophages, including CD206 and TGFB1." (PMID 37234161, 2023). "Glioma cells release a range of chemokines (CSF-1, MCP-1 and others) to recruit and activate TAMs, which then secrete the anti-inflammatory cytokines IL-10 and TGFB1." (PMID 37837549, 2023). "Similarly, expression of the TGFβ1 response gene, TACSTD2 (or TROP2), in cancer tissue (e.g., human glioma) has been shown to correlate with microvessel density—a commonly used marker for estimation of angiogenesis." (PMID 38132326, 2023). "RT-PCR and Western blotting were used to conclude that TGFβ1 expression (p < 0.01) was higher in gliomas compared with brain tissues without pathological changes." (PMID 35454784, 2022).
glioma (continued). "While it is a direct TGFβ1 target gene in microglia, the role of microglia-derived OLFML3 in glioma progression is unknown." (PMID 34884869, 2021). "Through western blot analysis, we observed that knocking down BACE2 suppressed EMT stimulated by TGFβ1 (10 ng·mL−1) in both U87MG and U251 cells, which indicated that BACE2 may be stimulated by TGFβ1 in glioma cells." (PMID 31856384, 2020). "An IL-8-dependent recruitment of MSCs was detected in glioma, and it has also been shown that platelet-derived growth factor subunit B (PDGFB), vascular endothelial growth factor (VEGF), and transforming growth factor beta-1 (TGF-β1) can induce MSC migration." (PMID 33117154, 2020). "This study reports TGFβ1 stimulates beta‐site APP‐cleaving enzyme 2 (BACE2) expression through Smad‐dependent signalling, which modulates TNF‐α‐induced NF‐κB activity through the PP1A/IKK pathway to promote tumorigenesis in glioma cells." (PMID 31856384, 2020). "In addition, neutralization of TGFβ1 in the co-culture of primary murine CD133+ glioma stem-like cells and TAMs attenuated the invasiveness of the CD133+ glioma stem-like cells." (PMID 32283687, 2020). "One study reports that the expression of FAT1 is positively correlated with that of TGFβ1/2 in human gliomas, primary glioma cultures, and other cancer cell lines (U87MG, HepG2, Panc-1, and HeLa cells), and that FAT1 silencing results in decreased expression and secretion of TGFβ1/226." (PMID 38782965, 2024). "Furthermore, TGFβ1 stimulates BACE2 expression through Smad‐dependent signalling, which modulates TNF‐α‐induced NF‐κB activity through the PP1A/IKK pathway to promote tumorigenesis in glioma cells." (PMID 31856384, 2020). "Inhibition of TGFB1 by miR-744 thus fulfills a dual role in mediating effects of this intronic miRNA on its host MAP2K4: (i) Functional antagonization via blocking SMAD-signaling, thereby reducing glioma migration and invasion; and (ii) control of the tumorigenic host’s expression levels." (PMID 30366472, 2018). "It has been proposed that glioma CSCs express differentiation markers similar to those in normal glia and neurons, such as of oligodendrocytes (ASCL1, OLIG2 and DLL3), astrocytes (GFAP), neurons (β-tubulin III, SYT1 and SLC12A5), and markers of inflamed astroglial cells (SERPINE1, TGFB1 and RELB)." (PMID 31661894, 2019).
colorectal cancer (734 papers, 1996 to 2026). A primary or metastatic malignant neoplasm that affects the colon or rectum. "Some cases of colorectal cancer are hereditary, therefore, in the next stage of the statistical analysis, an association between the relative level of TGFB1 gene expression and presence of cancer in a patient's immediate family was determined." (PMID 35798776, 2022). "In this case-control study, we examined the distribution of the allele and genotype frequencies of TGFB1 -509C/T polymorphism in colorectal cancer patients and its association with serum and tumor tissue TGF-β1 expression in a gender-dependent manner." (PMID 30071009, 2018). "The genotype distribution and allele frequencies of the -509C/T SNP in the TGFB1 gene promoter among colorectal cancer patients and healthy controls." (PMID 30071009, 2018). "PTPRK is also a transforming growth factor β1 (TGFβ1) target gene in mammary epithelial cells, synoviocytes and keratinocytes, and has been implicated as a tumour suppressor in several cancer types, particularly colorectal cancer." (PMID 38904097, 2024). "In another meta-analysis, Yang Liu and colleagues suggested that the T-allele of the TGFB1 -509C/T polymorphism might contribute to a decreased risk in colorectal cancer susceptibility, especially in Caucasians." (PMID 30071009, 2018). "Moreover, murine models deficient of the anti-inflammatory cytokine IL10 develop pronounced colitis, are predisposed to inflammation associated colorectal cancer, and display overexpression of TGFβ1." (PMID 27270652, 2017). "Spp1+ macrophages engage in the remodeling of ECM via TGFB1 signal in fibroblasts, thereby elevating the expression of MMPs and the deposition of collagens in colorectal cancer." (PMID 40664639, 2025). "The study shows that Nit1 contribute to the progression of colorectal cancer through regulating TGFβ1-Smad2/3 signaling pathway." (PMID 40740246, 2025). "Although data on IL6 mRNA levels are not shown due to undetectable expression in the SW620 cell line, PPARG and TGFB1 mRNA levels decreased after colorectal cancer tumorsphere generation." (PMID 39336151, 2024). "The overexpression of miR-21-5p downregulated TGFB1 expression in colorectal cancer cells, triggering cell pyroptosis." (PMID 38362150, 2024). "Western blot assays showed that CRC_sEVs were enriched in TGFβ1 compared with the cells, indicating that colorectal cancer cells secrete TGFβ1 into the surrounding environment through sEVs." (PMID 37072829, 2023). "In colorectal cancer, HIF1A, MMP9, and PTGS2 had the highest mutation frequency at 5.8%, 7.7%, and 5.8%, respectively, while in melanoma, PPARG and TGFB1 had the highest mutation frequency at 4.7% and 1.9%, respectively." (PMID 37033970, 2023). "Patients and methods: The effect of 5-FU on the expression of SMAD4 and TGFB1 in colorectal cancer cells derived from the CACO-2, SW480 and SW620 cell lines was evaluated using real-time PCR." (PMID 37237640, 2023). "Nevertheless, in all assessed colorectal cancer cell lines treated with 1 μM 5-FU solution, at both exposure times, a decrease in TGFB1 gene expression was observed." (PMID 37237640, 2023). "The first assessment focused on a comparison between the age of the patients in the study group at the time of developing colorectal cancer and the relative mRNA level of the TGFB1 gene." (PMID 35798776, 2022). "The involvement of the TGFB1 gene in the progression of colorectal cancer has been extensively described." (PMID 35798776, 2022). "While the TMEM91 gene was the reported candidate gene for the colorectal cancer risk at the rs1800469, we find that the risk variant affected three proteins in either cis (B3GNT8 and TGFB1) or trans (B3GNT2)." (PMID 35079000, 2022). "The results presented in the study prove a potential involvement of the TGFB1 gene in the development of colorectal cancer and its progression, however, they should be confirmed in a larger group of patients." (PMID 35798776, 2022).
colorectal cancer (continued). "The decreased expression of the TGFB1 gene found in colorectal cancer with high clinical advancement stages indicates that the loss of the physiological function of the gene and the protein it encodes is conducive to disease progression." (PMID 35798776, 2022). "Colorectal cancer patients have high TGFβ1 levels compared to healthy controls, and high levels of TGFβ1 are positively correlated with advanced tumor stage and metastasis after surgical resection." (PMID 36119489, 2022). "Co-culturing hepatocytes with various colorectal cancer cell lines enhanced TGFβ1 expression in the hepatocytes." (PMID 34376784, 2021). "To evaluate the effect of RUNX1 in TGFβ1-mediated invasion in colorectal cancer cells, we conducted a wound-healing assay using three different colorectal cancer cell lines including HT29, SW620, or COLO320dm." (PMID 34376784, 2021). "Transforming growth factor-beta 1 (TGF-β1) can upregulate the B7-H3 expression and pave the way for immune evasion of colorectal cancer cells via the miR-155/miR-143 axis." (PMID 33800752, 2021). "Inhibition of TGFBR1 can block the activation of fibroblasts mediated via IL1B/TGFB1 and reduce the secretion of pro-inflammatory cytokines in colorectal cancer, which would make the cancer cells more sensitive to chemotherapy." (PMID 32582282, 2020). "We also examine, in detail, the pervasive involvement of TGFβ-1 signaling from both cancer cells and CAFs in fostering cancer development, taking colorectal cancer (CRC) as a paradigm of human neoplasia." (PMID 29495500, 2018). "Colorectal cancer tissue expression of TGFB1 gene mRNA correlates with tumor progression and metastasis." (PMID 30071009, 2018). "More recently, Rojas and co-workers showed that TGFBR2 expression levels can affect the ability of TGFβ1 to induce p21 and apoptosis in the V-400 colorectal cancer cell line." (PMID 23951322, 2013). "To summarise, we have investigated the prognostic significance of the angiogenic marker CD105 and its ligands TGFβ1 and TGFβ3 in patients with colorectal cancer by immunohistochemistry and ELISAs." (PMID 12778073, 2003). "However, another report suggests that αSMA+ CAFs promote the differentiation of colorectal cancer stem cells through the BMP4/TGFβ1 signaling pathway, thereby inhibiting Lgr5+ CSCs." (PMID 37124519, 2023). "The obtained results indicate that lowering the level of TGFB1 gene expression may be one of the factors contributing to the progression of colorectal cancer." (PMID 35798776, 2022). "The high relative expression levels of the TGFB1 gene observed in the study in the least clinically advanced colorectal cancers may prove these findings." (PMID 35798776, 2022). "On the other hand, decreased level of the TGFB1 gene expression during the course of the disease observed in this study, may be an important result in the pathogenesis of colorectal cancer allowing for its further development." (PMID 35798776, 2022). "Similarly, we observed that the knockdown of TGFβRII diminishes the function of TGFβ1 towards RUNX1 expression in colorectal cancer cells." (PMID 34376784, 2021). "TGFβ1 plays a crucial role in colorectal cancer cells EMT and cell invasion." (PMID 34376784, 2021). "Within the TGFb super family, TGFb1, TGFb2, and TGFb3 play roles in these oncogenic processes and elevated systemic TGFb levels have been found to be correlate to poor prognosis factor in colorectal cancer." (PMID 30728909, 2019).
colorectal cancer (continued). "In order to ascertain if this strong expression of CD105 in the tumour vasculature is reflected in patients' plasma, circulating levels of CD105, TGFβ1 and TGFβ3 together with the receptor–ligand complexes were quantified in patients with colorectal carcinoma and normal controls." (PMID 12778073, 2003). "The protective role of the TGFB1 gene is confirmed by higher expression levels obtained in patients whose blood vessels are not affected by tumor cells and in presence of lymphocytic infiltration in cancer tissue, which are positive prognostic factors for colorectal cancer." (PMID 35798776, 2022). "The transforming growth factor-β (TGF-β) pathway exerts a tumor-suppressive function in cancer and is frequently inactivated by mutations in epithelial cancer cells, but elevated expression of TGFB1 mRNA (encoding TGF-β) is associated with poor outcome in colorectal cancer patients." (PMID 31296856, 2019). "High ACSL3 expression has been detected in a variety of cancers and is correlated with a poor prognosis in patients with these diseases, and ACSL3-mediated fatty acid oxidation is required for TGFβ1-induced EMT and metastasis in colorectal carcinoma." (PMID 40299526, 2025). "Further analyses showed that αSMA+ CAFs in colorectal cancer inhibited the proliferation of Lgr5+ CSCs and promoted the differentiation of CSCs through BMP4/TGFβ1 signaling pathway, exerting tumor suppressive effects and inhibiting the CRC progression." (PMID 37124519, 2023). "From the proteins annotated to the KEGG pathways colorectal cancer and PI3K-AKT signalling, one peptide of the TGF-β signalling proteins TGFB1 and TGFBR2 was detected in sEVs but not in the whole-cell lysates." (PMID 36648961, 2023). "In colorectal cancer/melanoma, ALKBH5 accelerated expression of angiogenic genes, such as VEGFA and TGFβ1, which weakened the efficacy of GVAX/anti–PD-1 therapy." (PMID 36291060, 2022). "In colorectal cancer/melanoma, the ALKBH5 inhibitor ALK-04 downregulated expression of VEGFA and TGFβ1, thus inhibiting angiogenesis and enhancing efficacy of anti–PD-1 therapy." (PMID 36291060, 2022). "We additionally confirmed that TGFβ1 and CLDN4 engage in molecular structural interactions and that TGFβ1 inhibits CLDN4 transcription and protein expression in human colorectal cancer cell lines." (PMID 35281827, 2022). "Here, we demonstrate that transforming growth factor beta 1 (TGFβ1) induces the up-regulation of ACSL3 through sterol regulatory element-binding protein 1 (SREBP1) signaling to promote energy metabolic reprogramming in colorectal carcinoma (CRC) cells." (PMID 35414781, 2022). "From the previous experiment, the TGFB1 and SERPINE1 were further analyzed concerning their expression in colorectal cancer and normal tissue." (PMID 34215248, 2021). "Taken together, these results implied that proper RUNX1 function is necessary for TGFβ1 signaling in EMT and cell invasion in colorectal cancer cells." (PMID 34376784, 2021). "GO and KEGG pathway analysis indicated that they were involved in multiple signaling pathways, including TGFβ1 signaling, the VEGF/Wnt/Jak-STAT signaling pathway, as well as pathways in the cell cycle, cancer and colorectal cancer." (PMID 33767593, 2021). "The effect of TSP1 on TGFβ1 expression by hepatocytes was further ascertained by generating TSP1-silenced HT29 and LS174 colorectal cancer cells and co-culturing them with IHH cells." (PMID 34376784, 2021). "Using TCGA colorectal cancer RNAseq and protein expression data, we demonstrated that WNT5A and TGFB1 were positively correlated with SMARCD3; WNT5A and TGFB1 were overexpressed in SMARCD3 high group." (PMID 33125346, 2020). "For example, alterations in the TGFB1 (transforming growth factor beta 1, TGF-beta) signaling have been implicated in colorectal carcinogenesis, and loss-of-function mutations in TGFBR2 (TGFB1 receptor 2) may serve as prognostic biomarkers for colorectal cancer patients." (PMID 29552640, 2017).